CACNA1C (calcium voltage-gated channel subunit alpha1 C)
Diseases named in the same sentence as CACNA1C in open-access papers (continued):
Sharing a sentence is not in itself a finding about the gene and the disease.
Timothy syndrome (continued). "For example, use of two mutually exclusive CACNA1C exons (8 and 8a), which are mutated in the syndromic autism spectrum disorder (ASD) Timothy Syndrome (TS), is developmentally controlled." (PMID 36102617, 2022). "Pathogenic variants in the L‐type Ca2+ channel gene CACNA1C cause a multi‐system disorder that includes severe long QT syndrome (LQTS), congenital heart disease, dysmorphic facial features, syndactyly, abnormal immune function, and neuropsychiatric disorders, collectively known as Timothy syndrome." (PMID 33797204, 2021). "In addition, mutations of calcium channels have been found in ASD, for example, CACNA1A rs7249246/rs12609735 were associated with Chinese Han ASD, and CACNA1A mutations in Epileptic Encephalopathy, gain of function of CACNA1C in Timothy syndrome with ASD and recurring CNVs of CACNA2D3." (PMID 33338084, 2020). "Specifically, mutations in the CACNA1C gene cause an abnormal function of this calcium channel, and have been associated with BP, SCZ and another syndromic form of ASD, Timothy syndrome (TS)." (PMID 30185603, 2018). "A zebrafish cacna1c loss of function allele caused developmental defects in ventricular cardiomyocytes and lower jaw development; however gain of function phenotypes relevant to Timothy syndrome, and effects on brain structure and function have not been examined." (PMID 40568156, 2025). "Moreover, there are three atypical LQTS or multisystem syndromic disorders including Ankyrin-B syndrome gene ANK2 (LQT4), Anderson–Tawil syndrome (ATS) gene KCNJ2 (LQT7), and Timothy syndrome (TS) gene CACNA1C (LQT8)." (PMID 38666937, 2024). "Timothy Syndrome (TS) (OMIM #601005) is a rare autosomal dominant syndrome caused by variants in CACNA1C, which encodes the α1C subunit of the voltage-gated calcium channel Cav1.2." (PMID 34079780, 2021). "These include Andersen–Tawil syndrome (LQT7, KCNJ2) in which skeletal developmental abnormalities are observed; Timothy syndrome (LQT8, CACNA1C) with characteristic neurological, facial and limb features and JLNS syndrome, associated with sensorineural deafness (KCNQ1-KCNE1 genes)." (PMID 35052786, 2022). "“Cardiac only” Timothy syndrome (COTS) shows no extracardiac manifestation, whereas some CACNA1C gene mutations are associated with QTc prolongation alone (isolated long QT syndrome 8, LQT8)." (PMID 36523353, 2022). "A significant number of individuals with a CACNA1C variant do present with non-syndromic LQT8, but do not have Timothy Syndrome." (PMID 34079780, 2021). "Novel genetic alterations in CACNA1C were also described by Wemhöner and colleagues, causing typical long QT syndrome (LQTS) without any clinical features of Timothy syndrome and leading to a gain-of-function activity of the channel combining different mechanisms." (PMID 31426283, 2019).
schizophrenia (158 papers, 2012 to 2026). A major psychotic disorder characterized by abnormalities in the perception or expression of reality. "Genome-wide association studies have consistently linked CACNA1C single nucleotide polymorphisms to schizophrenia, bipolar disorder, and related conditions." (PMID 42028275, 2026). "Consistent with our study, the CACNA1C gene has been suggested as a risk factor for schizophrenia in a GWAS study." (PMID 40259965, 2025). "Common and rare variation in CACNA1C gene expression has been consistently associated with neuropsychiatric disorders such as schizophrenia, bipolar disorder, and major depression." (PMID 40565009, 2025). "CACNA1C has been identified as a susceptibility locus in multiple psychiatric disorders, including bipolar disorder, schizophrenia, and autism spectrum disorder." (PMID 40725423, 2025). "Variants of CACNA1C have been associated with bipolar disorder and several neuropsychiatric disorders, such as schizophrenia, major depressive disorder, autism spectrum disorder, attention deficit hyperactivity disorder, and substance-use disorders." (PMID 39228919, 2024). "Cell lines derived from BP patients in this study harbor a single nucleotide polymorphism, rs1006737, in the L-type calcium channel gene CACNA1C, which mediates calcium influx into the cell and has been associated with BP as well as with schizophrenia." (PMID 39056776, 2024). "The microRNA 137 has been proved as a potentially risk for schizophrenia, and the CACNA1C, one target of microRNA 137, influenced the development process of schizophrenia." (PMID 38773596, 2024). "Cell lines were derived from carriers of a single nucleotide polymorphism, rs1006737, in the L-type calcium channel gene CACNA1C, which has been associated with both BP and schizophrenia." (PMID 39056776, 2024). "CACNA1C has been repeatedly identified in GWAS of schizophrenia and causes arrhythmia associated with autism." (PMID 38167462, 2024). "The rs1006737 variant (minor allele: A) of the CACNA1C gene is associated with cognitive impairment in patients with bipolar disorder and schizophrenia spectrum." (PMID 39228919, 2024). "GRM3 and CACNA1c, which respectively encode G protein-coupled receptors and ion channels, are typical targets for schizophrenia drug therapy in this context." (PMID 36936681, 2023). "Multiple genome-wide association studies point to variants in the CaV1.2 gene, CACNA1C, as major risk factors for schizophrenia, bipolar disorder, and other mental diseases." (PMID 37338965, 2023). "Cav1.2 is encoded by the CACNA1C (Ca2+ Voltage-Gated Channel Subunit Alpha1 C) gene which has been found to be a risk gene for schizophrenia, bipolar and major depressive disorder." (PMID 35844244, 2022). "For instance, CACNA1C is an important gene for schizophrenia, encoding the L-type calcium channel Cav1.2, which is a target of available schizophrenia drugs, as well as the heart repolarization function." (PMID 35136033, 2022). "The CACNA1C locus has been linked to schizophrenia, which is one of the most conclusive findings from genetic research on mental health." (PMID 36421807, 2022). "CACNA1C rs2239063 C was associated with schizophrenia (p = 1.93 × 10−8) and treatment response to olanzapine (p = 1 × 10−8) at a genome-wide significance level." (PMID 36421807, 2022). "The gene CACNA1C, which encodes the pore forming subunit of the L-type calcium channel CaV1.2, is associated with increased risk for neuropsychiatric disorders including schizophrenia, autism spectrum disorder, major depression, and bipolar disorder." (PMID 36550186, 2022). "Beyond that, some other SNPs in CACNA1C have been identified as risk loci for schizophrenia over the past years." (PMID 35990059, 2022). "Meta-analysis of GWAS as well as clinical studies have associated CACNA1C risk locus rs1006737 with susceptibility to schizophrenia and bipolar disorders." (PMID 35013113, 2022).
schizophrenia (continued). "In search of channel-encoding genes that are associated with both CADF and schizophrenia, CACNA1C and KCNH2 are promising candidates." (PMID 36421807, 2022). "Variants in CACNA1C are risk factors for autism and other psychiatric disorders such as schizophrenia." (PMID 35782381, 2022). "Three loci have been reported to have combined association with both schizophrenia and BD (CACNA1C, CACNB2, and ITIH3-ITIH4), and one locus, which was previously found to be associated with BD (NCAN)." (PMID 34502224, 2021). "There were no significant GO associations for the other protein subgroup (the CACNA1C as a center node), but these proteins were connected through publication studies with psychiatric diseases, such as schizophrenia, bipolar disorder, depression, and others." (PMID 34681041, 2021). "The association of rare deleterious mutations in genes encoding VGCC subunits, including CACNA1C, with schizophrenia and other neurodevelopmental disorders further supports the view that decreased CACNA1C expression can contribute to disease risk." (PMID 33597718, 2021). "Variants of the CACNA1C voltage-gated calcium channel gene have been associated with autism and other neurodevelopmental disorders including bipolar disorder, schizophrenia, and ADHD." (PMID 33829152, 2021). "For instance, CACNA1C is a gene involved in synaptic plasticity that has been linked to bipolar disorder, schizophrenia, major depressive disorder, and ASD." (PMID 34828381, 2021). "CACNA1C, a gene that encodes an alpha-1 subunit of L-type voltage-gated calcium channels, has been strongly associated with psychiatric disorders including schizophrenia and bipolar disorder." (PMID 31910256, 2020). "Additional rs1006737 meta-analysis showed an association between this CACNA1C polymorphism and schizophrenia in both the Europeans and Asians when the samples were stratified by ethnicity." (PMID 32770953, 2020). "CACNA1C, which encodes for the Cav1.2 α1 subunit of L-type calcium channels (LTCCs), is one of the best-supported risk loci for schizophrenia and bipolar disorder since it harbors variants with consequences on neural processing and connectivity." (PMID 32194626, 2020). "The L-type calcium channel gene, CACNA1C, is a validated risk gene for schizophrenia and the target of calcium channel blockers." (PMID 33139710, 2020). "The CACNA1C gene was defined as a risk gene for schizophrenia in a large genome-wide association study of European ancestry performed by the Psychiatric Genomics Consortium." (PMID 32770953, 2020). "The CACNA1C rs1006737, rs2007044, and rs4765905 gene polymorphisms were associated with the susceptibility to schizophrenia." (PMID 32770953, 2020). "A recent meta-analysis of the CACNA1C gene and schizophrenia contained nine studies on the association between rs1006737 and schizophrenia." (PMID 32770953, 2020). "CACNA1C was the most significant pleiotropic gene in terms of association with schizophrenia, as it also survived correction for the BIP GWAS, PBIP = 1.72 × 10−9." (PMID 32398653, 2020). "Previous meta-analyses focused on the association between the CACNA1C gene rs1006737 and schizophrenia." (PMID 32770953, 2020). "The α1C subtype is encoded by the CACNA1C gene, which is considered a risk factor for schizophrenia based on a large genome-wide association study (GWAS) of European ancestry performed by the Psychiatric Genomics Consortium (PGC)." (PMID 32770953, 2020). "This meta-analysis study advanced our understanding of the relationship between CACNA1C polymorphisms and schizophrenia compared to previous literature." (PMID 32770953, 2020). "Rs1006737, rs2007044, and rs4765905 of the CACNA1C gene were associated with susceptibility to schizophrenia." (PMID 32770953, 2020).
schizophrenia (continued). "While the most statistically robust CACNA1C associations are in BD, polymorphisms in CACNA1C shown to be correlated with other conditions such as schizophrenia, major depressive disorder (MDD), anxiety, neuroticism and obsessive–compulsive thoughts." (PMID 32411272, 2020). "Specifically, mutations in CACNA1C are amongst the most consistently detected genetic risk factors in both bipolar disorder and schizophrenia." (PMID 31554851, 2019). "We therefore conducted a meta‐analysis integrating nine studies under four different genetic models to evaluate the association of rs1006737 in the CACNA1C gene with schizophrenia." (PMID 31033230, 2019). "Common and rare variants of the CACNA1C voltage-gated calcium channel gene have been associated with autism and other neurodevelopmental disorders including schizophrenia, bipolar disorder and ADHD." (PMID 31805042, 2019). "Our findings contributed important evidence for the establishment of CACNA1C as a susceptibility gene for schizophrenia across world populations, but further investigations on its role in the pathogenesis of schizophrenia are warranted." (PMID 31033230, 2019). "Our findings provide important evidence for the establishment of CACNA1C as a susceptibility gene for schizophrenia across world populations, but its roles in the pathogenesis of schizophrenia need to be further investigated." (PMID 31033230, 2019). "The mutations in CACNA1C were observed in various types of human diseases, such as ventricular fibrillation, and schizophrenia." (PMID 31787999, 2019). "A growing body of evidence implicates several calcium and potassium channels in the susceptibility of schizophrenia, such as CACNA1C (Cav1.2 α subunit), KCNN3 (SK3), KCNH3 (Ether-A-Go-Go), and KCNJ3 (Kir3.1)." (PMID 31920555, 2019). "Genome‐wide association studies (GWAS) have identified the α‐1C subunit of the L‐type voltage‐gated calcium channel (CACNA1C) gene as a significant risk gene for schizophrenia." (PMID 31033230, 2019). "Although CACNA1C was strongly associated with schizophrenia in previous studies, it is still unclear how it affects the onset of schizophrenia." (PMID 31033230, 2019). "Recently, GWAS have identified the α‐1C subunit of the L‐type voltage‐gated calcium channel (CACNA1C) gene as a significant risk gene for schizophrenia." (PMID 31033230, 2019). "For example, disrupted in schizophrenia 1 (DISC1), neuregulin 1 (NRG1) and CACNA1C mutations and polymorphisms are known to be associated with schizophrenia, bipolar disorder and major depression." (PMID 29794033, 2018). "CACNA1C gene in particularly has been repeatedly shown to be genetic susceptibility genes for schizophrenia in different types of population." (PMID 28860957, 2018). "Genomic wide association studies identified the CACNA1C locus as genetically associated with both schizophrenia and bipolar affective disorder." (PMID 29501388, 2018). "Like MIR137, CACNA1C has been repeatedly linked to schizophrenia and bipolar disorder with genome-wide significance." (PMID 30618607, 2018). "In earlier studies there were sex-specific differences in influences of CACNA1C variants on mood disorders and functional recovery from episodes of schizophrenia." (PMID 28792954, 2017). "Specifically, the CACNA1C gene has been associated with severe psychiatric illnesses such as depression, bipolar disorder, autism, and schizophrenia, for which it has been listed as a risk gene." (PMID 28604818, 2017). "CACNA1C is also an associated gene of the one of the most highly significant SNPs for both bipolar disorder and schizophrenia in a cross-disorder genome wide analysis." (PMID 27115429, 2016). "Specifically, genome wide association studies (GWAS) have repeatedly identified the single nucleotide polymorphism (SNP) rs1006737 in intron 3 of CACNA1C to be strongly associated with schizophrenia and bipolar disorder." (PMID 27276213, 2016).
schizophrenia (continued). "Although the majority of studies have implicated these risk alleles in bipolar disorder, a number of studies suggest that variations in CACNA1C are associated with major depression, schizophrenia, and autism." (PMID 27957527, 2016). "This has been confirmed by recent genome-wide association studies showing CACNA1c as a susceptibility gene for schizophrenia in the worldwide population." (PMID 26685921, 2016). "The present study employed an imaging genetics strategy to investigate the effect of CACNA1C rs2007044, a schizophrenia susceptibility SNP first identified by our previous study and then confirmed by a recent GWAS, on cortical surface area and thickness." (PMID 27683010, 2016). "Previously, we identified CACNA1C rs2007044 as a new risk locus for schizophrenia, with the minor allele G as risk allele." (PMID 27683010, 2016). "Genetic variants in the CACNA1C gene have been reported in multiple diseases such as arrhythmia, bipolar disorder, and schizophrenia.32, –34 Further studies are needed to explore the functional role of CACNA1C in diabetic cataract." (PMID 27124316, 2016). "For CACNA1C (SNP rs2007044), the odds ratio for schizophrenia was 0.912 for the common allele (P = 3.22e-18)." (PMID 26386135, 2015). "Two mutations in CACNA1C were identified; this was one of the calcium channel genes previously implicated in several studies by GWAS of both bipolar disorder and schizophrenia (see section above)." (PMID 26386135, 2015). "Significant association between CACNA1C (calcium channel, voltage-dependent, L type, alpha 1C subunit) and schizophrenia was detected." (PMID 26204268, 2015). "It has been reported that genes encoding VGCC subunits, especially CACNA1C, are associated with psychiatric disorders, such as schizophrenia and bipolar disorder." (PMID 26136667, 2015). "Recently, another independent GWAS identified that rs4765905 in CACNA1C was associated with schizophrenia (p = 1.23×10−8)." (PMID 26204268, 2015). "For example, in a recent study, SNP rs4765905 in CACNA1C showed an association with schizophrenia with an odds ratio of 1.0944 and P = 1.2e-8." (PMID 26386135, 2015). "For example, the risk variant of the alpha 1C subunit of the L-type voltage-gated calcium channel (CACNA1C) gene is associated with schizophrenia, bipolar disorder and major depression." (PMID 24574956, 2014). "These included genes linked to bipolar disorders and schizophrenia, such as CACNA1C and DISC1, as well as the COMT gene." (PMID 24409157, 2014). "The variant at rs1006737 in the L-type voltage-gated calcium channel (alpha 1c subunit) CACNA1C gene is reliably associated with both bipolar disorder and schizophrenia." (PMID 25290268, 2014). "Previous large sample genetic association studies have supported a role of the CACNA1C minor allele in bipolar disorder and schizophrenia." (PMID 24944871, 2014). "Several genetic studies have implicated the CACNA1C SNP rs1006737 in bipolar disorder (BD) and schizophrenia (SZ) pathology." (PMID 23437284, 2013). "For example polymorphisms in CACNA1C have been associated with bipolar disorder, schizophrenia and major depression." (PMID 24278029, 2013). "Recent genome-wide association studies have identified CACNA1C as a candidate gene in bipolar disorder, schizophrenia, and autism." (PMID 23613729, 2013). "Variations in CACNA1C are linked to psychiatric disorders, including schizophrenia, and miR-137’s interaction with CACNA1C may modulate calcium influx into neurons, influencing synaptic plasticity and neuronal excitability." (PMID 40779062, 2026). "Genetic variation in CACNA1C, which encodes the pore-forming subunit of L-type voltage-gated calcium channel (L-VGCCs) Cav1.2, is consistently linked to an increased risk for neuropsychiatric disorders, including schizophrenia and bipolar disorder." (PMID 40565009, 2025).